PCNX4 (pecanex 4)
Synonyms: C14orf135; PCNXL4
Tractability: Antibody: UniProt predicts a signal peptide or a membrane-spanning region. PROTAC: ubiquitination databases record sites on it.
Gene: Protein-coding gene on chromosome 14 (60,091,911 to 60,169,133, forward strand). Ensembl gene ENSG00000126773.
Subcellular location: Membrane
Subcellular location (Human Protein Atlas): Cytosol
Gene Ontology:
Molecular function: protein binding
Cellular component: membrane
Genetic constraint (gnomAD): Loss-of-function variants: 94 observed, 105.62 expected, observed/expected ratio (o/e) 0.89, 90% interval 0.75 to 1.06. The upper end of that interval is the gene's LOEUF score, 1.06, which puts it in group 4 of 6, group 1 being the genes least tolerant of losing a copy. Missense variants: 1,481 observed, 1,398.7 expected, observed/expected ratio (o/e) 1.06, 90% interval 1.01 to 1.11. Synonymous variants: 526 observed, 490.1 expected, observed/expected ratio (o/e) 1.07, 90% interval 1 to 1.15.
Homologues: Orthologues: chimpanzee PCNX4 (99% identical), macaque PCNX4 (96% identical), dog PCNX4 (85% identical), pig PCNX4 (85% identical), rabbit PCNX4 (80% identical), guinea pig PCNX4 (79% identical), mouse Pcnx4 (77% identical), rat AABR07064804.1 (71% identical), tropical clawed frog pcnx4 (61% identical), zebrafish pcnx4 (51% identical). Paralogues in human: PCNX2 (19% identical), PCNX1 (19% identical), PCNX3 (19% identical).